SNORA10B (small nucleolar RNA, H/ACA box 10B)
Gene: Small nucleolar RNA gene on chromosome 2 (30,187,434 to 30,187,566, forward strand). Ensembl gene ENSG00000207187.
Gene Ontology:
Biological process: RNA processing
Cellular component: nucleolus
Homologues: Orthologues: chimpanzee SNORA10B (99% identical). Paralogues in human: SNORA10 (98% identical), SNORA64 (62% identical).